TLR2 (toll like receptor 2)
Diseases named in the same sentence as TLR2 in open-access papers (continued):
Sharing a sentence is not in itself a finding about the gene and the disease.
infection (continued). "Upon infection, Mtb interacts with several pattern recognition receptors (PRRs), of which engagement with TLR2 serves majorly towards Mtb-mediated immune modulation." (PMID 27883091, 2016). "Many markers that are supposed to be involved in the activation of CD14, TLR4, and TLR2 on monocytes and macrophages during infections have also been studied." (PMID 27252945, 2016). "Significantly lesser induction of Bcl-2 was observed when TLR-2 was downregulated by siRNA transfection prior to infection." (PMID 27826299, 2016). "The implication of TLR2 and 4 in the control of the infection seems to be related to the generation of anti-bacterial CD8+ T cell activity and the maturation of dendritic cells, including the production of pro-inflammatory cytokines." (PMID 28119856, 2016). "Addition of the TLR2 agonist zymosan to M. smegmatis cultures prior to PBMC infection increased HIV infectivity of isolated CD4+ T cells 6.2-fold relative to untreated M. smegmatis cultures (p<0.01)." (PMID 26807859, 2016). "The innate cellular response to the initial stages of infection is mediated by Toll like receptor (TLR2, TLR4, TLR9) signaling, these receptors have been shown to recognize the surface proteins of CMV and RSV." (PMID 27340772, 2016). "After infection with either L. major promastigotes, L. mexicana promastigotes, of L. mexicana amastigotes, TLR2−/− mice presented with significantly larger lesions than wild type (WT) C57BL/6 mice at one or more time points post-infection (p.i.)." (PMID 27716391, 2016). "Infection of TLR2−/− mice with L. mexicana promastigotes yielded very similar results to that of L. major, with significantly increased lesions and parasite burdens." (PMID 27716391, 2016). "The bacterial load was significantly reduced by TLR2 or TLR4 activation before the infection (24 h p.i.: 19% or 12% reduction; 48 h p.i.: 39% or 60% reduction)." (PMID 27105429, 2016). "Similar to THP-1 MDM, hMDM showed an increase in TLR-2 expression post infection, and TLR-2 downregulation prior to infection prevented the increase in Bcl-2 levels." (PMID 27826299, 2016). "The TLR2 immunoexpression was most intense at 2 and 4 dpi, and the immunointensity decreased during the time of infection." (PMID 27511368, 2016). "Acute TLR-2 ligation enhances both innate and adaptive immune functioning, permitting containment of the infection." (PMID 26927066, 2016). "After ex vivo infection with L. braziliensis, the expression of TLR2 and TLR4 increased significantly in monocytes isolated from CL patients (32 ± 26 versus 90 ± 64, and 14 ± 7 versus 55 ± 32, respectively), p<0.001." (PMID 26840253, 2016). "Clearly, MEK/ERK acted as the downstream effectors of TLR-2 after infection with the L. donovani parasite leading to Bcl-2 increase favoring parasite survival." (PMID 27826299, 2016). "After infection, MDMs were stimulated with TLR2/1L or IFN-γ and bacterial viability relative to respective media control was determined after three days of treatment." (PMID 27355424, 2016). "We investigated whether infection of THP-1 macrophages by BCG-OtsB2 was associated with changes in cell-surface expression of a number of immune-related receptors including a number of receptors such as TLR2, TLR4, Mincle, Dectin-1 and CD-14 that have been implicated in phagocytosis of mycobacteria." (PMID 27867377, 2016). "Wild-type mPM showed a gradual increase in TLR-2 expression post infection with an increase in Bcl-2 levels." (PMID 27826299, 2016). "TLR2 and its co-receptor TLR6 have also been found to play a role in disease pathogenesis during infection with the filarial parasite, Brugia malayi, which causes lymphatic filariasis." (PMID 26897363, 2016). "Previous work from our group identified a TLR2-mediated increase in HIV infectivity of CD4+ T cells following infection of PBMC with M. bovis BCG compared to M. smegmatis." (PMID 26807859, 2016).
infection (continued). "Intracellular WCH-SK2WT infection induced mRNA expression of TLR2, pro-inflammatory cytokines (IL1B, IL6, and IL12) and tissue remodeling factors (MMP9)." (PMID 28083514, 2016). "In the initial stage of infection, parasite DNA and surface glycoconjugates are able to trigger innate immune response through TLR-2, -4 and -9 in macrophages and dendritic cells, enhancing their endocytic capacity and killing by oxidative burst." (PMID 26090667, 2015). "Several recent findings have suggested the pro-inflammatory role of TLR2 in different infection models." (PMID 25658110, 2015). "The resultssuggest that infection of L. major directlyinduces upregulation of TLR2 only in BMDDCs from resistant (C57BL/6) mousestain." (PMID 25738770, 2015). "We first infected BMDDCs from both mousestrains with L. major and treated them withthe TLR2 agonist Pam3CSK4, either at the time of infection, or 18 h postinfection." (PMID 25738770, 2015). "To investigatewhether those changes in TLR2 expression were a direct consequence of infection,we employed CFSE-labeled parasites to directly track the infected cells." (PMID 25738770, 2015). "Further strengthening the idea that TLR-2 signaling induces proliferation of Tregsin vivo, and similar to a previous study, we observed reduced Tregs at the site of infection in C. albicans infected Tlr-2−/− mice compared to WT mice." (PMID 25790134, 2015). "Eight genes (NCF4, CD14, IL17D, CD1D, CD163, IL1R2, TLR9, and TLR2) with different expression in each infection group were selected for qPCR analysis." (PMID 25906258, 2015). "Working with an infection model similar to the one used by Leendertse, we were able to examine the consequences of overstimulation of the TLR2 system on the natural course of peritoneal infection." (PMID 26172831, 2015). "And in agreement with previous works, production of mature IL-1β in response to Ft LVS infection is dependent on TLR2 and the inflammasome adaptor ASC." (PMID 25768794, 2015). "TLR2 plays an important role in resistance to the infection induced by Mycobacterium tuberculosis (Mtb)." (PMID 26208853, 2015). "We isolated macrophages from wild type and ERK, TLR-2, and MyD88 knock-out mice, infected these cells with H37Rv or H37RvΔTlyA, and investigated bacterial loads at different time points post-infection." (PMID 25847237, 2015). "In order to access if there was a difference in monocyte activation after the infection with Y strain or Col cl1.7, we analyzed the expression of HLA-DR and TLR-2." (PMID 26147698, 2015). "TLRs are important in host resistance, and there is evidence that TLR2, 4, 9 and 11 are involved in recognition of T. gondii although knockout of no single TLR results in the high susceptibility observed following infection of MyD88−/− mice." (PMID 26528819, 2015). "Indirect evidence in favour of this can be found in a previous study where we observed tlr2 and tlr5-expressing cells migrating from secondary to primary lamellae during the first hours post-infection with V. vulnificus." (PMID 26207370, 2015). "Surprisingly, while infection with Y strain and Col cl1.7 both led to an increase in the intensity of expression of HLA-DR and TLR-2, the two isolates affected differently the expression of CD80 and CD86." (PMID 26147698, 2015). "Mock-infected and DV2-infected PBMC were harvested on day 3 post-infection and stained for TLR2/TLR6 and CD14." (PMID 26226614, 2015). "To investigate the role of TLR2 directly sensing HIV-1 structural proteins and contributing to increased infection and pro-inflammatory cytokine production, we tested primary human T cells and a TLR2 stably transformed TZMbl cell line (TZMbl-2)." (PMID 26347747, 2015). "The in vitro findings demonstrating involvement of TLR2 are in agreement with the observation that in vivo infection with P. gingivalis/F." (PMID 26158901, 2015). "It was reported that chromatin remodelling involving DNase I and restriction enzyme occurs at TLR2 promoter region following infection." (PMID 26226614, 2015).
infection (continued). "Since these changes occur early after activation, we evaluated the expression of HLA-DR and TLR-2 after 15 hours of infection." (PMID 26147698, 2015). "The widely accepted mechanism is that lipid-modified membrane proteins and diacylglycerol-containing glycolipids of the spirochete signal via CD14 and/or Toll-like receptor 2 (TLR2)/TLR1 heterodimers to promote a proinflammatory response during infection." (PMID 26697208, 2015). "Further, our finding that TLR2 expression significantly increased HIV integration via increased CCR5 expression provides a mechanism by which HIV-1 can regulate host infection and persistence." (PMID 26347747, 2015). "The temporal profile of TNF production by S. pyogenes-infected cells was consistent with a largely host cell surface-localized TLR2-dependent S. pyogenes recognition early in the infection and an endosome-dominated recognition in the later phase." (PMID 25756897, 2015). "Taken together, these results indicate that miR-UL112-3p expressed by HCMV during infection efficiently down-regulates endogenous TLR2." (PMID 25955717, 2015). "Several studies have shown that infection with P. acnes involves an interaction with TLR2 and TLR4 on keratinocytes." (PMID 26197393, 2015). "Early TLR2 accumulation was followed by a down-regulation phase clearly seen at 4 and 6dpi, which corresponded to the late phase of infection as indicated by the detection of pp65, a late gene product." (PMID 25955717, 2015). "A series of components of Mtb can trigger the TLR2 signaling pathway upon infection, such as triacylated lipoprotein LprG, LpqH and PhoS1, and glycolipid lipoarabinomannan." (PMID 26208853, 2015). "The local innate immune response of mammary glands was swiftly activated after S. aureus inoculation during the initial stage of infection, characterized by up-regulation of gene expression of TLR2, NOD2, TNF-α, IL-1β, IL-6, and CXCL1." (PMID 25990971, 2015). "Our data provide insights into the role of TLR2 in infection with T. gondii, with implications for the pathophysiology of the disease." (PMID 26528819, 2015). "The contribution of TLR2-depedent pathway was more apparent in cDCs but it became less visible with increasing time of infection." (PMID 25756897, 2015). "LTA treatment of THP-1 cells resulted in TNF induction similar to infection with S. pyogenes suggesting that S. pyogenes was recognized through TLR2." (PMID 25756897, 2015). "In order to determine cellular mechanisms involved in the induction of Camp upon infection with M. avium in BMMφ, we started by analysing if TLR2 is involved, given that this bacterium acts as a TLR2 agonist." (PMID 25400920, 2014). "The high levels of serum IFN-γ, but not those for TNF-α during an infection with S. mansoni is dependent on ligands for TLR2 and/or TLR4, because in mice deficient for both TLRs serum IFN-γ was low throughout the infection." (PMID 25398130, 2014). "In conclusion, our report demonstrates that similar cell surface innate immune receptors (CD36, SR-A, MARCO and TLR2) play different roles against S. aureus infection, depending on the site of infection." (PMID 24498223, 2014). "To further pinpoint the underlying cellular mechanism of these microbial effects on TLR2 and TLR4 expression we used a sterile infection cell culture model." (PMID 25396415, 2014). "The host response to F. tularensis is driven by TLR2 signaling initiated from phagosomes at the earliest stages of infection, and the TLR-MyD88-NF-κB pathway is also critical for miR-155 induction." (PMID 25295729, 2014). "For example, we have shown that F. novicida significantly increased TLR2 transcript after infection in primary monocytes while F. tularensis Schu S4 decreased it." (PMID 24600590, 2014). "Mouse macrophages are found to produce IFN and other cytokines in response to infection by Candid#1 virus and presumably by pathogenic JUNV as a result of host recognition of viral glycoprotein protein in a TLR-2-dependent manner." (PMID 24901990, 2014).
infection (continued). "Studies in mice with genes from inactivated TLRs have shown that TLR2 expression in monocytes is important in infection control and survival in these animals." (PMID 24558401, 2014). "Our study revealed that ChoD interacts directly with macrophages via TLR2 and influences the biological activity of macrophages during the development of the initial response to infection." (PMID 25120288, 2014). "The differential ability of TLR2/1 activation to induce antimicrobial activity against M. tuberculosis or M. leprae negatively correlated with the induction of hsa-mir-21 during infection, where M. leprae induced hsa-mir-21, but M. tuberculosis did not." (PMID 25076967, 2014). "The ability of TLR2 KO mice to produce these cytokines, even if at reduced levels compared to B6 mice, indicates that infection with wild-type LVS inhibits other immune signaling pathways in addition to TLR2." (PMID 25250027, 2014). "Third, TLR2-mediated respiratory epithelium responses to infection by S. pneumoniae increase tight junction breakdown and bacterial translocation across epithelial layers." (PMID 25172490, 2014). "In a kinetic study, we found that the strain 26695 and the virB4– and virD4– mutants reduced TLR2 expression 3, 6, and 24 h after infection (and 3C respectively), although this reduction was only significant after 24 h for all three strains." (PMID 23755130, 2014). "Infection of BMMφ, TLR2/6 activation or treatment with TNF, all led to an increase of Camp mRNA levels." (PMID 25400920, 2014). "The involvement of TLR2 was confirmed by the infection of macrophages derived from TLR2-knockout mice." (PMID 24732131, 2014). "Several proteins with significant SVVs identified from the network structure variations during infection are involved in the immune response, such as Tlr2 and B2m." (PMID 24757665, 2014). "The immunomodulatory activity of ArtinM was previously demonstrated by studies in which lectin administration induced Th1 immunity in P. brasiliensis-inoculated mice and conferred protection against infection in a TLR2-dependent manner." (PMID 24892697, 2014). "Here, we found that mouse cathelicidin (Camp) expression was induced in bone marrow-derived macrophages by infection with Mycobacterium avium in a TLR2- and TNF-dependent manner." (PMID 25400920, 2014). "Toll-like receptor TLR2 and TLR4 have also been found to be necessary for effective innate immune control of infection; however, the immunological responses underlying the differences between infection of reservoir and incidental hosts remain a mystery." (PMID 25437801, 2014). "We measured IL1β, TNF, IL10, IL12, IL23, IL17, and IL4 production from human peripheral blood mononuclear cells (PBMCs) stimulated with a panel of clinical isolates from the airways and infections and measured the ability of these isolates to stimulate TLR2." (PMID 25209732, 2014). "Cathelicidin expression was strongly impaired in TLR2-null macrophages, demonstrating that the induction of Camp mRNA upon infection with M. avium depends on the activation of TLR2." (PMID 25400920, 2014). "With a sterile infection cell culture model and siRNA silencing of TLR2 we were able to specifically pinpoint the induction of the epithelial proliferation response to TLR2." (PMID 25396415, 2014). "One effect of the cumulative hsa-mir-21-mediated regulation of the cellular gene expression was ultimately control of the TLR2/1 antimicrobial activity against the infection." (PMID 25076967, 2014). "TLR4 is capable of inducing type I interferon production via either MYD88 or the alternative adapter TRIF, but infection of Tlr2/Tlr4 double knock-out cells induced antiviral gene expression, ruling out a role for TLR4 as well." (PMID 24505488, 2014). "We found that Mtb HN878-infection of TLR-2−/− lung DCs, had a dramatic impairment in IL-1β production when compared to infection of B6 DCs, and coincided with low IL-17 production in DC: lung cell co-cultures." (PMID 24831696, 2014).